ANKRD20A4P (ankyrin repeat domain 20 family member A4, pseudogene)
Synonyms: OTTHUMG00000066855; formerly ANKRD20A4
Gene: Transcribed unprocessed pseudogene on chromosome 9 (64,369,675 to 64,438,574, forward strand). Ensembl gene ENSG00000172014.
Genetic constraint (gnomAD): Loss-of-function variants: 0 observed, 14.99 expected, observed/expected ratio (o/e) 0, 90% interval 0 to 0.2. The synonymous counts are far from expectation, so gnomAD's model fits this gene poorly and the ratio says little. Missense variants: 23 observed, 191.41 expected, observed/expected ratio (o/e) 0.12, 90% interval 0.085 to 0.17. Synonymous variants: 4 observed, 60.35 expected, observed/expected ratio (o/e) 0.0663, 90% interval 0.032 to 0.15.